OR51I2 (olfactory receptor family 51 subfamily I member 2)
Description:
Odorant receptor.
Synonyms: OR11-38
Tractability: Antibody: UniProt places it where antibodies can reach, with medium confidence; UniProt predicts a signal peptide or a membrane-spanning region; its Gene Ontology location is reachable by antibodies, with medium confidence.
Gene: Protein-coding gene on chromosome 11 (5,449,323 to 5,456,518, forward strand). Ensembl gene ENSG00000187918.
Subcellular location: Cell membrane
Pathways (Reactome):
Sensory Perception: Expression and translocation of olfactory receptors
Gene Ontology:
Molecular function: olfactory receptor activity; G protein-coupled receptor activity; signaling receptor activity
Biological process: sensory perception of smell; cellular response to lipid; detection of chemical stimulus involved in sensory perception of smell; G protein-coupled receptor signaling pathway; system process
Cellular component: membrane; plasma membrane
Genetic constraint (gnomAD): Loss-of-function variants: 6 observed, 9.51 expected, observed/expected ratio (o/e) 0.63, 90% interval 0.34 to 1.24. That is too few expected variants to judge how well the gene tolerates losing a copy. Missense variants: 430 observed, 367.09 expected, observed/expected ratio (o/e) 1.17, 90% interval 1.08 to 1.27. Synonymous variants: 151 observed, 130.71 expected, observed/expected ratio (o/e) 1.16, 90% interval 1.01 to 1.32.
Homologues: Orthologues: chimpanzee OR51I2 (99% identical), mouse Or51i2 (89% identical), rat Or51i2 (89% identical), rabbit OR51I2 (87% identical), guinea pig OR51I2 (84% identical). Paralogues in human: OR51I1 (60% identical), OR51G2 (56% identical), OR51G1 (53% identical), OR51E2 (53% identical), OR51F2 (53% identical), OR51C1 (52% identical), OR51L1 (52% identical), OR51E1 (52% identical), OR51M1 (51% identical), OR51D1 (50% identical), OR51A7 (50% identical), OR51A4 (49% identical), and 39 more.